AR (androgen receptor)
Diseases named in the same sentence as AR in open-access papers (continued):
Sharing a sentence is not in itself a finding about the gene and the disease.
endometrial cancer (continued). "The expression of androgen receptor (AR) is not commonly tested or studied in uterine cancers, unlike estrogen receptor (ER) and progesterone receptor (PR) which are positive in most endometrial carcinomas." (PMID 37725629, 2023). "However, in endometrial cancer, KDM4B modulates AR activity to promote endometrial cancer progression and was identified as a hub gene for cancer development by bioinformatics analysis." (PMID 35186950, 2021). "As AKR1C3 catalyzes formation of the potent androgen which can activate androgen receptor and can thus inhibit proliferation this supports the hypothesis of the anti-proliferative role of AKR1C3 in endometrial cancer." (PMID 33352741, 2020). "Expression levels of ERα, AR, and 17β-HSD2 in endometrial cancer cell lines were examined." (PMID 29642629, 2018). "We find that high expression of ATAD2 predicts poor outcome and significantly associates with markers for aggressive endometrial cancer, such as high FIGO stage and high grade, non-endometrioid type, and loss of hormone receptors AR, PR and ERα." (PMID 26308378, 2015). "Further evaluation of not only EGFR ligands and HER3 levels but also AR levels and markers of EMT may help to define patients with EGFR-expressing endometrial cancer most likely to respond to lapatinib." (PMID 18334972, 2008). "In addition, AR is positive in these high-grade endometrial cancers lacking ER or PR expression." (PMID 36358974, 2022). "Therefore, the endometrial cancer Hec1A cell line is an ER-α66-negative and AR-negative cell line." (PMID 19775474, 2009). "Expression of EGFR, its ligands, HER3, AR, and post-EMT markers warrant further evaluation to help define patients with HER2-nonoverexpressing endometrial cancer most likely to benefit from lapatinib." (PMID 18334972, 2008). "The findings of this study imply that the downregulation of AR and absence of PR gene expression in AN3 cells, could be contributing to the uncontrolled proliferation, seen in endometrial cancer cells." (PMID 35372016, 2022).
diabetes (50 papers, 2008 to 2026). "The expression of AR gene seems susceptible to females in diabetes patients, probably due to the loss of ERα." (PMID 40362356, 2025). "Gaining an in-depth understanding of the AR mutations underlying PCOS with diabetes will deepen our understanding of the endocrine factors involved in the disease etiology, and provide potential targets for treatment." (PMID 40486679, 2025). "Previous studies have demonstrated that androgen receptor-mediated endocrine resistance was associated with diabetes." (PMID 35936218, 2022). "In the present study, diabetes caused a significant decrease in the expression of AR in the DC and DSh groups, compared to the HC rats (P < 0.001)." (PMID 32607132, 2020). "In this review, we summarize the structural basis and interactions between androgen receptor and EDCs as well as the associations of various types of diabetes mellitus with the EDCs mediated through androgen receptor binding." (PMID 29295509, 2017). "EDCs that binding androgen receptor have been reported associated with diabetes mellitus in in vitro, animal, and clinical studies." (PMID 29295509, 2017). "Endocrine disrupting chemicals mediated through AR have been found associated with diabetes mellitus." (PMID 29295509, 2017). "Comparative analysis on the diseases associated with AR and the chemicals interacted with AR found that 13 androgenic chemicals are associated with diabetes mellitus." (PMID 29295509, 2017). "Eight of the 20 AR genes carrying rare H variants, have been directly associated to taste, food intake, body size, diabetes or triglyceride levels." (PMID 27566279, 2016). "Initial studies of db/db mice deficient in AR suggested that AR contributed to the diabetes-induced abnormalities in the retina, including breakdown of the blood-retinal barrier, loss of pericytes, and even an effect on neovascularization was claimed." (PMID 23614016, 2013). "In addition to ER, abnormal expressions of AR are associated with obesity and diabetes mellitus in PCOS." (PMID 35885010, 2022). "During diabetes, reduction of testosterone levels might be due to changes in the body composition, androgen receptor polymorphisms, glucose transport and decreased level of antioxidants." (PMID 27869771, 2016). "In addition, we found that this downregulation of AR induced by diabetes is associated with significant tumor growth retardation in an in vivo model of PCa." (PMID 24058525, 2013). "Since then, AR has been found also to regulate a variety of additional abnormalities (including oxidative stress and inflammation) that have been implicated in the pathogenesis of various complications of diabetes and other diseases." (PMID 23614016, 2013). "Also the radical scavenger Nelumbo nucifera inhibits AR, which may suppress the production of ROS associated with the polyol pathway, thus preventing the complications of diabetes." (PMID 30373222, 2018). "The association between T levels and BAA is affected by several biological mechanisms such as the concentration of binding proteins, body mass index, certain diseases (e.g., diabetes), androgen receptor (AR) sensitivity, and different cofactors." (PMID 35230239, 2022). "Increased AR expression in PCOS also causes dysregulation in hepatic glycogen in the absence of insulin resistance, leading to hyperglycaemia and diabetes mellitus." (PMID 35885010, 2022). "Two of the included articles performed multivariate Cox survival analysis including tumor stage, myometrial invasion, race, BMI, diabetes, and AR, ER, and PR expression." (PMID 35814433, 2022). "The relationship between AR pathway and diabetes or hypertension deserves further investigation because, to the best of our knowledge, the role played by HSD3B1 with these comorbidities has never been investigated." (PMID 35874037, 2021). "Regarding lifestyle impact, we encountered only a few studies investigating AR expression in correlation to BMI and/or diabetes." (PMID 33915941, 2021).
diabetes (continued). "It has also been demonstrated that high glucose in diabetes leads to the up-regulation of AR in several tissues and the treatment with specific AR inhibitors prevents hyperglycaemia-induced hyperplasia and hyper proliferation of vascular smooth muscle cells." (PMID 28399135, 2017). "One week of diabetes decreased the AR immunostained cells by 40% compared to group C1, and MLT treatment did not prevent this depletion (p < 0.0001)." (PMID 26295055, 2015). "Deletion of AR largely (P<0.05) inhibited the diabetes-induced degeneration of retinal capillaries, as well as the increase in superoxide production by retina." (PMID 23614016, 2013). "AR inhibitors were reported to inhibit diabetes-induced abnormalities in oxidative stress, inflammation, and apoptosis in the retina." (PMID 23614016, 2013). "In contrast, retinal GSH tended to be subnormal in wild-type diabetics, but deletion of AR had little effect on this diabetes-induced reduction." (PMID 23614016, 2013). "In contrast, retinas from AR−/− diabetic animals exhibited significantly fewer diabetes-induced acellular capillaries." (PMID 23614016, 2013). "Since recent data suggests an important role for leukocytes in the development of the retinopathy, we determined also if AR in leukocytes contributes to leukocyte-mediated death of retinal endothelial cells in diabetes." (PMID 23614016, 2013). "IAD and/or administration of exogenous androgen at a concentration 2500-3500 ng/dl will benefit patients with AR-rich relapsed tumors by suppressing tumor growth, improving quality of life, and reducing risks for cardiovascular diseases and diabetes." (PMID 21859492, 2011). "We find that following exposure to T, or the selective AR-agonist dehydrotestosterone (DHT), CF mice challenged with STZ, which are normally protected, are prone to β-cell failure and insulin-deficient diabetes." (PMID 20585581, 2010). "Thus, identifying potent AR inhibitors can pave the way for effective therapies against diabetes and related complications." (PMID 37050122, 2023). "One possible explanation for this phenomenon could be the elevated androgen receptor signaling in men with diabetes." (PMID 36431238, 2022). "The present study aims to study the relationship between AR polymorphism, IR, β-cell function and other clinical/biochemical parameters in a cohort of ethnic South Asian adults with and without diabetes." (PMID 29202793, 2017). "Recent studies have also been focused on its pharmacological effects against diabetes and found several potential targets including α-amylase and α-glucosidase, but the AR inhibitory effect of diosgenin and its effects against sugar cataract is a new area that has never been investigated before." (PMID 29038789, 2017). "This study examined whether pre- and cotreatment with MLT interferes with tissue damage induced in the prostate of Wistar rats by experimental diabetes, particularly in terms of proliferative activity, apoptosis, and AR expression." (PMID 26295055, 2015). "It is worthy to mention that short-term diabetes drastically reduced the frequency of AR-positive cells in the prostate and this effect probably persists at later stages of the disease as previously reported by our research group after one-month of streptozotocin-induced diabetes." (PMID 26295055, 2015). "Use of AR inhibitors revealed a variety of diabetes-induced alterations in retinal metabolism that could be manipulated." (PMID 23614016, 2013). "Consistent with this, reported inhibition of diabetes-induced defects in electroretinogram using pharmacologic inhibitors was not confirmed using AR−/− mice studied by us, raising a possibility that some of the observed effects of AR inhibitors were due to off-target effects." (PMID 23614016, 2013).
diabetes (continued). "The present results using C57Bl/6 mice that are deficient in AR demonstrated that this genetic modification substantially (but not totally) inhibited the diabetes-induced degeneration of retinal capillaries, and totally inhibited superoxide generation by the retina in diabetes." (PMID 23614016, 2013). "In addition, the downregulation of AR induced by diabetes was associated with a tumor growth reduction or even no tumor growth in the PAC120 PCa mouse model treated with STZ." (PMID 24058525, 2013). "Of note, AR and PCC have been documented to ameliorate inflammatory responses in a variety of diabetic complications, such as diabetic nephropathy and diabetes‐induced cognitive impairment, through the reduction in Nlrp3 and Caspase1 levels." (PMID 37621124, 2023). "Enhancing AR LOF is likely to exacerbate sexual dysfunction, metabolic syndrome and diabetes, depression, and muscle atrophy." (PMID 36746939, 2023). "The main goal of this study was to determine the relationships between trinucleotide repeats of the androgen receptor (AR), sex steroids, and pituitary hormones with sexual function in men with type 2 diabetes mellitus (DM) and reported with acquired premature ejaculation (PE)." (PMID 29556396, 2018). "In the present study we explored the relationship between AR CAG repeat length, IR, diabetes status and other clinical/biochemical parameters in a cohort of ethnic South Asian males." (PMID 29202793, 2017). "We were unable to demonstrate any significant relationship between the number of AR CAG repeats and the presence of diabetes, hypertension, ischaemic heart disease, stroke, cirrhosis and chronic kidney disease." (PMID 29202793, 2017). "Diabetes of 10 mos duration did not cause a significant decrease in the number of cells in the retinal ganglion cell layer in these C57Bl/6 mice (not shown), so we could not assess any effect of the AR deletion on neurodegeneration." (PMID 23614016, 2013). "Could this response be related to a genetic alteration in the androgen receptor, or to changes in the hypothalamic-pituitary-adrenal (HPA) axis, or to the diabetes that is characteristic of this strain?" (PMID 31108549, 2019). "Expression of iNOS and ICAM-1 in whole retina were significantly increased by diabetes compared to that of wildtype nondiabetic animals (both p<0.05), but deletion of AR inhibited the diabetes-induced enzyme induction only for iNOS." (PMID 23614016, 2013). "It had been reported that the mouse was not a reasonable animal model in the research of diabetes drug, because of its much lower AR expression level than that of human, which was probably insufficient to generate toxic by products." (PMID 23282076, 2012). "Indeed, AR gene expression in DRG male rats is not affected by short-term diabetes (data not shown)." (PMID 29351809, 2018). "Surprisingly, the AR knockout did not inhibit several diabetes-induced molecular abnormalities that previously have been found to contribute to the retinopathy, suggesting that multiple molecular pathways contribute to the vascular lesions of the retinopathy in mice." (PMID 23614016, 2013). "Deletion of AR also inhibited the diabetes-induced increase in expression of iNOS but not ICAM-1, which is interesting because both are regulated by NF-κB, and both have been shown to be strongly related to the capillary degeneration occurring in retinas of diabetic animals." (PMID 23614016, 2013). "However, the effect of diabetes on AR and tumor growth had never been explored." (PMID 24058525, 2013). "The mean AR CAG repeat length (± SD) in patients with and without diabetes was 22.3 ± 3.2 and 22.6 ± 3.0 respectively (p = 0.70)." (PMID 29202793, 2017).
gastric cancer (49 papers, 2006 to 2025). A primary or metastatic malignant neoplasm involving the stomach. "Further research has identified AR variants in gastric cancer tissues and cell lines, implicating them in promoting tumorigenesis and metastasis." (PMID 41228208, 2025). "AR activation by androgens initiates complex pathways stimulating cell proliferation and angiogenesis, increasing men’s susceptibility to gastric cancer." (PMID 38667536, 2024). "ESR1 and androgen receptor (AR) upregulation is associated with a poor prognosis in gastric cancer patients." (PMID 35267457, 2022). "Estrogen and androgen receptors (ER and AR, respectively) have been implicated in the development and progression of malignancies such as breast, prostate and gastric cancer." (PMID 33807519, 2021). "Since it has been shown that AR overexpresses in gastric cancer (GC) as a male-predominant tumor, the goal of this study was to evaluate the association between AR and AURKA and its prognostic value in GC patients." (PMID 31871591, 2019). "However, AR is likely to promote tumor growth and/or progression in esophagus, bladder, head and neck, and stomach cancers, and thus is associated with poor survival." (PMID 41228208, 2025). "In conclusion, this study demonstrated that hsa-miR-942-3p could be a potential prognostic marker of gastric cancer associated with the AR and MAPK/ERK signaling pathways." (PMID 36135175, 2022). "A few studies, mainly from Asian groups, have reported the expression levels of hormone receptors (ERs, PR and AR) in gastric cancers." (PMID 40868070, 2025). "The intricate interplay of the AR with oncogenic pathways profoundly influences gastric cancer development in men." (PMID 38667536, 2024). "Western blot assay was adopted to verify the TNF‐α/Androgen receptor/TGF‐β signalling pathway axis regulation on gastric cancer by oridonin." (PMID 37431884, 2023). "This study mainly aimed to investigate the role of TNF‐alpha/Androgen receptor/TGF‐beta signalling pathway axis in mediating the proliferation inhibition of oridonin on gastric cancer SGC‐7901 cells." (PMID 37431884, 2023). "More importantly, we detected the target gene AR of hsa-miR-942-3p which was the core target gene and closely related to the prognosis and survival of gastric cancer patients." (PMID 36135175, 2022). "At the same time, AR is a target gene of the has-miR-942-3p, which well verifies the important role of the has-miR-942-3p in the occurrence and prognosis of gastric cancer." (PMID 36135175, 2022). "Previous studies have shown that AR is a potential therapeutic target for gastric cancer, predominantly female patients." (PMID 34977116, 2021). "The present study has investigated the clinicopathological significance of AURKA expression in gastric cancer and the correlation with androgen receptor." (PMID 31871591, 2019). "miR-488 was reported to function as a tumor suppressor in human prostate and gastric cancer by targeting androgen receptor and PAX6." (PMID 29113360, 2017). "Our findings are inconsistent with a few previous publications in which ERα, PR and AR were proposed as adverse factors whereas ERβ was deemed beneficial for gastric cancer patients." (PMID 23199240, 2012). "Following the first detection of AR in 2 of 16 gastric cancer patients, a positive rate of 17.4% for AR nuclear staining in an immunohistochemical study of 86 cases was indicated." (PMID 23199240, 2012). "In the present study, the expression profile and prognostic role of ERα, ERβ, PR, and AR in gastric cancer was determined in a large Chinese cohort." (PMID 23199240, 2012). "Research has indicated that disruptions in AR homeostasis might contribute to the higher prevalence of gastric cancer in men compared to women." (PMID 41228208, 2025).